CD44 (CD44 molecule (IN blood group))
Diseases named in the same sentence as CD44 in open-access papers (continued):
Sharing a sentence is not in itself a finding about the gene and the disease.
tumor (continued). "Tumor volume of mice treated with paclitaxel alone was approximately 3-fold higher than in mice treated with combined HA-PEI/HA-PEG/MDR1 siRNA CD44 targeted nanopartricle and paclitaxel, which could reflect an increased chemosensitivity to paclitaxel in mice treated with HA-PEI/HA-PEG/MDR1 siRNA." (PMID 25687880, 2015). "Although studies in vitro indicate that the tumor promoting function of HA partly depends on its molecular weight, and on its capacity to interact with other proteins, many of the tumor promoting activities of HA could be explained by its interaction with CD44." (PMID 25999946, 2015). "By characterizing these novel molecular tumor markers, we hope to advance our understanding of the molecular and biological mechanisms involved in carcinogenesis and tumor progression and to find unique CD44 isoform and expression fingerprints of the varying cell types present in tumors." (PMID 24122205, 2014). "Thirdly, anti-CD44 mAb may inhibit GBC tumor growth by hampering apoptosis or angiogenesis." (PMID 24725816, 2014). "However, the size of tumor generated by CD24+/CD44+ cells was significantly larger than the size of the tumors from CD24-/CD44+ or unsorted control cells indicating CD24+/CD44+ cells are highly aggressive." (PMID 24612587, 2014). "The CD44 antigen is a cell-surface glycoprotein involved in cell-cell interactions and cell adhesion and migration, for these properties participate in a wide variety of cellular functions including lymphocyte activation, recirculation and homing, hematopoiesis, and tumor metastasis." (PMID 24959179, 2014). "CD44 is a novel type of molecule that may be involved in tumor growth, invasion and metastasis." (PMID 24708709, 2014). "Importantly, CD44 has been recognized as a cancer stem cell marker for a variety of tumor types." (PMID 24455486, 2014). "This may be as the CD44+ cells exhibited the correct intrinsic properties to form the tumours." (PMID 23833643, 2013). "Moreover, it induces several tumor characteristics typical of BLCs: extratumoral lymphovascular invasion, hematogenous metastatic spread, and increased expression of basal cytokeratins and CD44 in vivo." (PMID 24324613, 2013). "Therefore, CD44 might play a crucial role in the regulation of intracellular ROS, thus contributing to metastasis and drug resistance in tumor cells." (PMID 23803658, 2013). "Importantly, activation of signalling pathways initiated by the tumor matrix could be inhibited by HA degradation, by competition with small HA fragments, by CD44 blockade or by CD44 knockdown." (PMID 23445749, 2013). "Thus, the surface labeling intensity of CD44 expression may vary from 2 to 5 fold among tumor samples, and there is typically a large variance in average surface CD44 labeling within individual samples." (PMID 24019906, 2013). "Furthermore, shedding of the ectodomain of CD44 plays a critical role in tumor cell migration." (PMID 24403253, 2013). "Emerging studies show that CD44 is an important biomarker of a cellular subpopulation (cancer stem cells, CSCs), which are capable of self-renewal and have the capacity for initiation, progression, invasion, metastasis, tumor recurrence, and resistance to chemo- and radiotherapy." (PMID 24257075, 2013). "However it is noteworthy that only 60% of 100 cell CD44+CD24neg -injected animals formed tumours, suggesting that T-ISC frequency may also be decreased in this subset in MDA-MB-231 as well (right)." (PMID 23982961, 2013). "CD44+/CD24+ profiles was associated with tumor size and lymph node metastasis." (PMID 23419168, 2013).
tumor (continued). "Since then, several studies have demonstrated that CD44+ subpopulations, emanating from both primary tissues and cell lines, exhibit a higher potential for proliferation, differentiation, migration, invasion, tumour sphere formation, and resistance to chemotherapeutics." (PMID 23533441, 2013). "Thus, the functions of CD44 gene products in tumor biology are controversially discussed." (PMID 23565227, 2013). "In addition, the CD44+ H1299 cells are also tumour initiating cells in a xenograft model." (PMID 23651443, 2013). "These in vitro results indicate that HA depletion may result in anti-metastatic activity, as suggested by recent laminar flow assays which demonstrated that blockade of HA-CD44 interaction by CD44 antibody reduced tumor cell adhesion to HA in several CD44-expressing cancer cell lines." (PMID 24213471, 2012). "Kaplan-Meier analysis showed that the presence of CD44+/CD24-/low tumor cells was significantly associated with shorter OS compared with the absence of CD44+/CD24-/low tumor cells (39.3 ± 2.6 months versus 54.0 ± 3.5 months; Pearson chi-square, 12.140, p = 0.001)." (PMID 22762532, 2012). "Interestingly, CD44 has been revealed as a cancer stem cell marker for numerous tumor types." (PMID 23213537, 2012). "Since knockdown of CD44 was very effective to suppress cancer stem cell regeneration and metastasis, it will be interesting to examine whether there is any functional role for CD44 in LSChi;CD166hi tumor initiating cells." (PMID 22880034, 2012). "Thus the detection of high CD44 expression in tumor biopsy tissue may be a suitable biomarker to identify patients who may benefit from the provision of MT1-MMP- or uPA-targeting therapeutics to reduce the risk of intravasation and distant metastasis." (PMID 22621373, 2012). "Thus, it may be that whilst some CD44 isoforms provide a protective role, others may promote adverse cellular features that could favour tumour progression." (PMID 23039365, 2012). "Additionally, the bone microenvironment is rich in ligands such as OPN, which may further support CSC recruitment to the bone through interactions between tumor cell-surface receptors such as CD44." (PMID 22295241, 2012). "Functionally, the HA/CD44 interactions might contribute to tumour cell proliferation, because after inhibition of HA synthesis by 4-MU or application of shRNA targeting HAS3 the remaining proliferative activity of tumour cells was confined to the CD44 positive tumour cell - stroma interface." (PMID 21429221, 2011). "It was suggested that CD44 is required for the assembly of a soluble matrix which may serve as an exosome carrier and/or a reservoir for growth factors, chemokines, and proteases needed for tumor cell embedding and growth." (PMID 22190973, 2011). "Next we considered that upregulated CD44 may bind stromal HA to the tumour cell surface." (PMID 21429221, 2011). "However, since we base our analysis on nucleic acid extracts from homogenized tumor tissue, including a mixture of tumor and stromal cells, we cannot exclude the possibility that the different patterns of CD44 isoforms are influenced by the varying presence of infiltrating cells." (PMID 21957977, 2011). "Down-regulation of the Stress and calcium protein kinase C pathways might increase the sensitivity of CD44 knockdown BCSCs to some anti-tumor drugs, such as doxorubicin, because the Stress and protein kinase C pathways help cancer cells to cope with stress and changes of environment." (PMID 22152097, 2011). "Our results thus reveal that 1) not all DTCs are necessarily CSCs; 2) conventional chemotherapeutic drugs such as taxol and etoposide may directly target CD44+ tumor-initiating cells; and 3) DTCs generated via chronic drug selection involve epigenetic mechanisms." (PMID 21935404, 2011). "Furthermore, clinical studies indicate that CD44+/CD24- tumor-initiating cells express an invasive gene signature and may be associated with distant metastases." (PMID 21824412, 2011).
tumor (continued). "Collectively, these data indicated that the specific interactions of SDF-1 with their receptor CXCR4 that expressed on mammosphere cells are likely to occur in tumor-stromal niches, and these interactions may be responsible for the proliferation of CD44+CD24- cells." (PMID 20569497, 2010). "Therefore, it is tempting to speculate that the activity of PCBP1 could influence tumor cell invasion by regulating the CD44 v6 expression." (PMID 20361869, 2010). "Earlier, overexpression experiments have suggested that CD44 may exert a tumour-suppressive function, although other studies have implicated CD44 in CaP cell proliferation, adhesion, migration and invasion in vitro, as well as in metastatic dissemination in vivo." (PMID 20736947, 2010). "Notably, although the proportions of live CD44+ cells (47.73% for primary, 0.91% for secondary) were reduced on serial transplantation, the efficiency of tumor initiation increased in successive generations of tumor." (PMID 21124918, 2010). "Furthermore, CD44 is an important tumor marker which is released by cancerous cells and could be detected by blood tests to detect the presence of cancer." (PMID 19223963, 2009). "Moreover, long term culture of the tumor biopsies revealed HBCEC populations expressing certain precursor cell-like and tumor-associated markers, including CD24, CD44 and CD227, respectively, which was paralleled by little if any senescence and a detectable telomerase activity." (PMID 19751512, 2009). "In addition, it will be important to determine whether tumour initiation is a general feature of basal cells with high β1-integrin levels, or whether a combination of markers such as CD44, MCSP and Lrig1 will allow further enrichment." (PMID 18657901, 2008). "Therefore,CD44+/CD24−/low tumor cells could be a subclass oftumorigenic cells characterized by a great metastatic potential, maybe due tothe role of CD44 as a homing receptor for distant tissue compartments." (PMID 19325911, 2008). "CD44 variants bind to a wide variety of ECM constituents and growth factors which have been shown previously to play different roles in tumour invasion, motility and metastasis, and downregulation of their expression may be pivotal for the metastatic cascade to take place." (PMID 12439723, 2002). "Interestingly, CD44 may act as a tumor cell surface anchor for MMP-9, a matrix metalloproteinase, which may contribute to collagen degradation and contribute to tumor invasiveness." (PMID 19570245, 2002). "Prior studies have established that stemness markers, particularly CD44 and CD133, are essential for maintaining tumor cell survival and contribute to poor therapeutic outcomes 35-37." (PMID 41510165, 2026). "The cancer stemness markers CD44 and CD133 are key mediators of drug resistance, driving tumor survival and poor treatment responses." (PMID 41510165, 2026). "10.13039/100014337Furthermore, RT-qPCR analysis showed a significant decrease in the mRNA expression of MTOR, CD44, and SAA1 in the combination group, further supporting the synergistic effect of PF-309 and OXA in inhibiting tumor growth." (PMID 41459112, 2026). "Mechanistically, EC@HNA suppressed CREB phosphorylation at Ser133, which transcriptionally repressed key stemness regulators, including CD44, CD133, and NR4A1, thereby attenuating tumor stemness and immune evasion." (PMID 41510165, 2026). "SPP1+ TAMs secrete SPP1 to bind CD44 on CD8+ T cells, inducing exhaustion and impairing anti-tumor function." (PMID 41601649, 2026). "For tumor-infiltrating CD8+ T cells, nearly all were positive for the memory marker CD44, with the main populations being EM CD8+ T cells (CD62L- CD44+), followed by CM CD8+ T cells (CD62L+ CD44+)." (PMID 41542752, 2026). "Inhibition of CD44 or Wnt signaling with HH1 or a Wnt inhibitor effectively reversed macrophage-mediated chemoresistance and suppressed tumor growth and metastasis." (PMID 41993204, 2026).
tumor (continued). "At necropsy, tumor burden, ex vivo BLI metastasis, weights, H&E histology, and immunohistochemistry (Ki67, CD44, CD31, PD-L1) were assessed." (PMID 42192974, 2026). "TAMs facilitate tumor invasion, metastasis and immune evasion through secreted phosphoprotein 1 (SPP1) and interaction with the integrin family/CD44 axis in CAFs." (PMID 42156717, 2026). "EC@HNA inhibited phosphorylated CREB, which downregulated the stemness markers CD44 and CD133 and prevented resistant tumor cells from surviving therapeutic stress." (PMID 41510165, 2026). "LGR5, ALDH1, CD44, and CD133 are critical CSC markers for tumor growth, metastasis, and therapy resistance." (PMID 41438576, 2026). "Numerous markers for CSCs have been proposed across various tumor types, and advancements have been made by targeting CSC surface markers such as CD44, CD133, and EpCAM." (PMID 41368628, 2025). "To further characterize the proliferation status of CD44-expressing tumor cells during and after HER2 inhibition, we analyzed Ki67 positivity within CD24+ and CD44+ subpopulations." (PMID 40430044, 2025). "Altogether, tumor-derived OPN and its engagement with CD44 on CD8+ T cells present an additional checkpoint that dampens T-cell activation, and perhaps an exploitable vulnerability, that confers immunotherapy resistance." (PMID 40865052, 2025). "CD44 and CD133 staining further demonstrated that these treatments enhanced the presence of tumor cells with high stemness activity." (PMID 40225580, 2025). "Tumor cells that were positive for both ALDH1 and CD44 existed in 50% of the cases studied in this cohort." (PMID 40647395, 2025). "The tumour stemness‐related genes CD133, EpCAM, CD44, L1CAM, ROR1, CD371 and so forth are the main research targets." (PMID 40665579, 2025). "We have also examined the expression of several tumor aggressiveness markers (MMP‐9, CD44, CD34, PTTG, FGFR4, Ki‐67, E‐Cadherin, and N‐Cadherin) in AF, AD, and PF tumor cells of male rat pituitaries." (PMID 41017273, 2025). "Most notably, MIF–CD74_CD44 signaling, known to induce immune suppression and matrix metalloproteinase (MMP)-mediated tumor invasion, was markedly downregulated." (PMID 40941002, 2025). "Cell Adhesion and Migration: CD44, ITGB1, LAMB1, FAT1, PLAUR, and TGFBI are integral to cell–matrix interactions and extracellular matrix (ECM) remodeling, processes critical for tumor invasion and metastasis." (PMID 41303451, 2025). "The co-expression of CD166 and CD133 ranged from 0.19% to 53.6% (median 1.2%) and the co-expression of CD44 and CD166 ranged from 54% to 96.55% (median 86.6%) in the examined tumor tissue cell samples." (PMID 41303421, 2025). "Flow cytometry analysis reveals that CAS treatment increases splenic populations of CD3+CD8+ cytotoxic T cells, CD3+CD44+ memory T cells, and NK cells, while enhancing CD8+ T cell infiltration in tumor tissue." (PMID 40375992, 2025). "Tumor-derived OPN can also bind to αvβ3 integrin and CD44 on fibroblasts to activate Akt, ERK, and Twist1, all contributing to the CAF phenotype." (PMID 40865052, 2025). "Secondary tumor analysis revealed higher CD8+/CD4+ T cell infiltration and significant CD44+CD62L− effector memory T cell expansion, demonstrating systemic immune activation capable of suppressing distant tumors and establishing durable immune memory." (PMID 40892295, 2025). "These cells, which are marked by molecules such as CD24, CD44, CD133, and Hes3, have the ability to self-renew and differentiate into more mature cancer cells, aiding in tumor progression and the formation of pseudopalisading necrosis." (PMID 40223032, 2025). "Our CD44-targetingA6 peptide was conjugated to cholesterol-PEG4 on the surface of LNPsthrough a GGGKKKGK linker, thereby creating a tumor-specific deliverysystem that we refer to as AKPC-LNP." (PMID 40176316, 2025).
tumor (continued). "Emerging evidence suggests that cancer stem-like cell populations, characterized by markers such as CD44 and Protein kinase D1 (PKD1), contribute to intratumoral heterogeneity and tumor maintenance in PanNETs." (PMID 40648806, 2025). "In breast cancer, augmented enzymatic activity of HYAL1 and HYAL2 correlates with aberrant signaling through HA receptors (CD44, RHAMM), thereby promoting tumor progression, metastasis, and recurrence." (PMID 40646377, 2025). "Next, to demonstrate the selective differentiation-inducing effect of VPA in tumor cells, we evaluated the expression of the CSC markers Sox9, Axin2, Cd44, and Ascl2 in organoids isolated from healthy mouse intestines." (PMID 40750758, 2025). "These cells bore the CD44+/CD24− phenotype and had an innate ability to form heterogeneous tumors, much like the original tumor." (PMID 40318146, 2025). "We obtained 44 paired tumor samples (pre- and post-chemotherapy) from the Tumor Biobank, assessing BCSC biomarkers (CD44, CD24, and ALDH1), PD-L1, and percentages of stromal tumor-infiltrating lymphocytes (TILs)." (PMID 40362201, 2025). "A comprehensive analysis of ICPs revealed significantly higher levels of ICPs such as CD44, CD80, CD86, and CTLA-4 in the high-TKT expression group, thereby allowing tumor cells to evade immune surveillance, and facilitating tumor progression." (PMID 40230848, 2025). "Consistent with our results in cancer cells, the ECF-R tumor organoids had increased NINJ2 and CD44 mRNA levels compared with the parental tumor organoids." (PMID 40518514, 2025). "Mounting evidence indicates that CD44 acts as a marker for cancer stem cells and has a significant function in controlling CSC characteristics, including self-renewal, tumor initiation, metastasis, and resistance to chemotherapy and radiotherapy." (PMID 39941011, 2025). "Fascin overexpression enhances mammosphere formation and resistance, while its silencing reduces the CD44+/CD24− fraction, impairs stem-like features, and sensitises tumours to docetaxel." (PMID 40806254, 2025). "Hypoxia also elevates ZEB1/2 activity, increasing the proportion of CD44+CD117+ cancer stem cells from 5% to 18%, thereby enhancing tumor invasiveness." (PMID 40474872, 2025). "Studies have shown a positive correlation between elevated CD44 levels and higher WHO MG grades, highlighting its potential as a marker of tumour severity and a target for therapeutic intervention." (PMID 39316249, 2025). "According to literature reports, the interaction of Siglec-15 with its ligands CD44, MAG, and sialyl-Tn mediates immune escape in the tumor microenvironment, thus affecting the development of tumors." (PMID 40507880, 2025). "The findings suggest that CD44, CD90, CD133, and EpCAM were enriched in HCC tumor tissues, supporting their role in hepatocarcinogenesis." (PMID 40791212, 2025). "The presence of CD44 in the extracellular matrix of these tumors creates a substantial barrier, impairing the CAR NK cells’ ability to reach and effectively target the tumor antigens." (PMID 40075578, 2025). "Specifically, we analyzed the expression of CD44, CD133, and CD166 in tumor-derived cell populations and assessed their correlation with unstimulated salivary flow rates and relevant clinical parameters." (PMID 41303421, 2025). "CSCs are partially defined by specific cell surface markers, including CD133, CD44, CD90, EpCAM, and ALDH; however, the variability of these markers across tumor types poses challenges for their use as universal therapeutic targets." (PMID 40868290, 2025). "Driving lipid metabolic reprogramming and immunosuppression through MIF-(CD74+CD44)-mediated macrophage polarization, our work finds FOS as a master regulator of the malignant C0 MAFF+ tumor cell subtype in LUAD." (PMID 40936936, 2025). "Our finding revealed that significantly higher expression of all four studied markers CD44, CD90, CD133, and EpCAM in HCC tumor tissues compared to corresponding non-tumor tissues (P < 0.05)." (PMID 40791212, 2025).